NT5E (5'-nucleotidase ecto)
Diseases named in the same sentence as NT5E in open-access papers (continued):
Sharing a sentence is not in itself a finding about the gene and the disease.
tumor (continued). "Among the factors capable of evading immune surveillance and altering the tumour cell antigenic landscape, NT5E/CD73 has recently received great attention." (PMID 24741617, 2014). "AKAP12, DCBLD2, NT5E and SPON1 are particularly represented in the signatures and selected for validation in vivo on two independent patients cohorts comprising 140 tumor tissues and 60 matched normal tissues." (PMID 24133572, 2013). "We show that NT5E is a target of the TNF-α signaling in vitro; the tumor suppressor PPARγ acts as a novel NT5E antagonist that positively and concomitantly regulates DCBLD2 in a cancer cell context-dependent manner." (PMID 24133572, 2013). "This study identifies CD73 (NT5E) as a direct hypoxia-responsive effector of HIF1α and demonstrates that dual inhibition of HIF1α and CD73 synergistically suppresses tumor cell viability, disrupts adenosine metabolism, and impairs angiogenic and migratory signaling." (PMID 41463265, 2025). "While NT5E’s role in supporting EAC cell viability under hypoxia highlights its tumor-intrinsic functions, NT5E is best characterized for its contributions to the tumor microenvironment, where CD73-generated adenosine promotes immune evasion, angiogenesis, and metastatic potential." (PMID 41463265, 2025). "KCNN4 has been shown to have positive correlations with several costimulatory molecules (CD276, CD40, CD70, CD80, CD86), immune signaling receptors (IL2RA, MICB, NT5E), and multiple TNFRSF family members, suggesting its involvement in immune modulation, inflammation, and tumor‐immune interactions." (PMID 40952239, 2025). "NT5E (CD73), CSF ligands, CD274 (PDL1), IL1B, IL6, and IL10 transcripts were primarily found in the peri necrotic zone, whereas NOS2 (iNOS), TGFB2, and NOX1 expression is localized to cellular tumor regions." (PMID 39272914, 2024). "To test gene induction, we co-transfected them transiently with crRNAs and trans-activating CRISPR RNA (tracrRNA) to induce the transcription of genes commonly expressed by tumor cells (e.g. CD274, NT5E) or genes not expressed by tumor cells such as CD80." (PMID 37732732, 2023). "In addition, NT5E (CD73) widely exists in various types of tumor microenvironment (TME) cells, and it can promote the tumor via crosstalk between the tumor cell and TME." (PMID 37792675, 2023). "Upregulated CD73/NT5E expression in cancer cells results in the accumulation of immunosuppressive adenosine, which dampens the function of adenosine receptor (A2A)-expressing T cells and NK cells present in the tumor microenvironment." (PMID 37409119, 2023). "We have also noticed that the high expression level of CD73 (also known as NT5E) in LUAD is significantly correlated with poor OS, which may indicate that CD73 plays an indistinct role in tumor development." (PMID 36765073, 2023). "ENTPD1, IL17A, and P2RX7 were downregulated, while HSP90AA1, PIK3CA, and NT5E were upregulated, indicating that ENTPD1, IL17A, and P2RX7 might negatively affect tumor development and result in better outcome." (PMID 37587188, 2023). "Also of potential significance regarding the tumour immune microenvironment, is the presence of two immune checkpoint genes, CD276 (also known as B7-H3) and NT5E (also known as CD73) in the set of 938 signature DEGs that separate the clusters." (PMID 36207323, 2022). "Interestingly, commonly downregulated genes included c-Myc and c-Myc target genes, as well as additional pro-oncogenic factors, such as IL1B, NT5E (CD73), and other molecules with functions in tumor immune escape 38,39, which were validated by qPCR." (PMID 31554806, 2019). "NT5E (CD73) has emerged as a novel target for tumor immunotherapy approaches, since functional inhibition of NT5E reversed its immunosuppressive effects resulting in tumor immune attack and eradication of cancer cells by cytotoxic CD8+ T cells and NK cells." (PMID 29720980, 2018).
tumor (continued). "As expected, NB5t primary cells showed increased expression of mesenchymal genes (NT5E, ENG, ACTA2, MME, CD44, VIM or ALPL), while NB5t tumor sample expressed mostly neuronal genes (TH, ENO2, NCAM1, DDC or CHGB) reflecting the neuroblastic phenotype of stage 4/M NB tumors." (PMID 29163787, 2017). "We selected five genes, SPP1, COL1A1, NT5E, HTRA1 and ANGPT1, of 15 genes whose coding proteins could be secreted from the pituitary, and we examined their tumor expression in 118 CD patients." (PMID 27690016, 2016). "Besides the known tumor suppressor genes DOCK5 and PTEN, genes OXSR1, BSG, NT5E, PLEKHG7,CMTM8, NETO2, ODZ3, and ERBB4 adhered to our criteria and were qualified as novel candidate tumor suppressor genes." (PMID 25551557, 2014). "Tumor-derived vesicles were found tosignificantly increase the expression of genes having a verifiedimmunity-regulating function in activated CD4+ T cells, while innaïve cells, gene expression slightly increased only for FAS1, IL-10, andPTGS2, while decreasing for DPP4, CD40LG, and NT5E." (PMID 31993233, 2019). "In contrast to FAP+ cells and THY1+ cells, the overall percentages of NT5E+ cells, TNC+ cells, and PDGFRβ+ cells were not altered in the tumor microenvironment compared to benign prostate stroma." (PMID 33600062, 2021). "While the overall expression of NT5E, TNC, and PDGFRβ did not change in the tumor microenvironment, ASPN expression was altered in these cells." (PMID 33600062, 2021).
cancer (546 papers, 2012 to 2026). A tumor composed of atypical neoplastic, often pleomorphic cells that invade other tissues. "NT5E is frequently overexpressed, and its high expression is associated with advanced disease stage and poor survival across multiple cancers, including EAC." (PMID 41463265, 2025). "Remarkably, the 5′-nucleotidase NT5E is invariably associated to lower survival in four distinct cancer types, namely breast, brain, stomach, and pancreas." (PMID 38723607, 2024). "In the subsets of fibroblasts, cancer-associated fibroblasts (CAFs) specifically express oncogenes such as NT5E and FZD1." (PMID 36460803, 2023). "CD73, encoded by ecto-5′-nucleotidase (NT5E) gene, plays a vital role in adenosine signaling, and its overexpression correlates with poor prognosis in a variety of cancers." (PMID 36899373, 2023). "NT5E encodes CD73, which is an ectonucleotidase present on cancer cells that helps cancer cells convert ATP into adenosine." (PMID 36186454, 2022). "Cluster of differentiation (CD) 73, which is encoded by the NT5E gene, regulates production of immunosuppressive adenosine and is an emerging checkpoint in cancer immunotherapy." (PMID 33198064, 2020). "In particular, Nt5e (also known as CD73) is expressed by cancer cells and encodes for an ectonucleotidase that cooperates with CD39 to generate extracellular adenosine, which can in turns prevent T cells activation and proliferation." (PMID 31439856, 2019). "Hypoxia is a potent inducer of the expression of the cancer-associated enzyme ecto-5′-nucleotidase (NT5E/CD73)." (PMID 31547570, 2019). "Progression from preinvasive lesions to overt cancers was also associated to increased expression of potent immunosuppressive genes, among which Nt5e and Tgfβ1 have been previously shown to induce T cell dysfunction." (PMID 31439856, 2019). "This study provides a comprehensive view of ICD-related genes across cancers, identifies NT5E as a potential biomarker in HNSC, and highlights novel targets for predicting immunotherapy response and improving clinical outcomes in cancer patients." (PMID 41150760, 2025). "NT5E has been previously characterized as an immunosuppressive factor involved in response to ICI cancer therapy." (PMID 40759686, 2025). "Compared to other sites, bone metastases of both cancer types expressed higher levels of ENTPD1 and NT5E, which encode CD39 and CD73, respectively, and hydrolyze ATP to adenosine." (PMID 36186774, 2022). "ENTPD1 and NT5E, as important regulators of extracellular adenosine availability, facilitate evasion of the immune system by cancer cells." (PMID 36233136, 2022). "NT5E is a novel target for the treatment of many cancer types, and various NT5E/CD73 inhibitors are currently being tested in clinical trials." (PMID 35354498, 2022). "There is abundant evidence that ENTPD1 and NT5E expression are increased in cancer including in gastric cancer, non-small cell lung cancer and prostate cancer." (PMID 36233136, 2022). "The remodeling involves a particular increase in a cancer-associated fibroblast subtype, i.e., FAP+ fibroblasts, and a decrease in a mesenchymal stem-like cell subtype, i.e., NT5E+ fibroblasts." (PMID 35365629, 2022). "In gallbladder carcinoma, miR-30b inhibits the proliferation, metastasis, and invasion of cancer cells by targeting ecto-5′-nucleotidase (NT5E) and proline-rich transmembrane protein 2 (PRRT2)." (PMID 35291564, 2022). "The main sources of adenosine in cancer are typically CD39 and CD73, which are encoded by ENTPD1 and NT5E, respectively." (PMID 34307352, 2021). "Targeting NTPDase1/CD39, NT5E/CD73, adenosine or adenosine receptors is increasingly recognized as a promising intervention in anti-cancer therapy." (PMID 33613285, 2020). "CD73, a glycosylphosphatidylinositol (GPI)‐anchored protein encoded by the gene NT5E, reacts on the surface of immune cells, stromal cells and cancer cells." (PMID 32643277, 2020).
cancer (continued). "One of the membrane-bound enzymes which has been suggested to participate in NAD+ precursor uptake and metabolism is CD73 (NT5E), an enzyme that is often upregulated in cancer cells." (PMID 31959836, 2020). "Ecto-5′-nucleotidase (NT5E) is a glycosylphosphatidylinositol anchored cell surface protein, and has been suggested to be dysregulated in most types of human cancer including gastric cancer." (PMID 30992388, 2019). "CD117 positive fibroblast-like stromal cells were further identified by mesenchymal stem/stromal cell (MSC) marker CD73 (NT5E) and cancer associated fibroblast (CAF) markers fibroblast activation protein (FAP) and α-smooth muscle actin (α-SMA)." (PMID 25380303, 2014). "Our findings and those reported in the literature suggest a schematic and simplified model in which NT5E/CD73 metastasis-promoting actions appear to be the result of a close cooperation between cancer, stromal, and inflammatory cells." (PMID 24741617, 2014). "All together these results suggest that multiple mechanisms affect NT5E/CD73 expression in cancer and stromal cells (endothelial cells, fibroblasts, and TAM) contributing to the evolution of metastatic niches and evasion of immune surveillance." (PMID 24741617, 2014). "The role of NT5E/CD73 was recently summarized as a suppressor of anti cancer immune responses during carcinogenesis." (PMID 25469109, 2014). "Ecto-5′-nucleotidase (NT5E/CD73) is crucial in cancer and immune regulation." (PMID 41487509, 2025). "In addition, 1B3 reduced NT5E expression in several human cancer cell lines and there was a strong reduction in percentage CD73+ cells and MFI CD73 compared to mock and 3A1-transfected cells." (PMID 39007281, 2024). "Moreover, we described 5 genes associated with hypoxia high status, of which the top 3 (LGALS3, CD276 and NT5E) have already been identified as targets of interest in cancer." (PMID 38510243, 2024). "In this study, first, we found that NT5E is highly expressed in many cancers, including HNSCC." (PMID 35510041, 2022). "The important role of NT5E in many cancers has been demonstrated." (PMID 35510041, 2022). "In addition, we investigated some cancer stem cell markers and we demonstrated an increase in Cd44, Nt5e and Aldh1a1." (PMID 34670568, 2021). "Also, NT5E (CD73) inhibitors are currently being tested in several clinical trials for the treatment of cancer." (PMID 33854619, 2021). "The function of 5'-nucleotidase isoform 2 preproprotein (NT5E) in cancer is unclear." (PMID 33495406, 2021). "Moreover, the processing of RNAs coding for NT5E is regulated by a miRNA group, the presence of this miRNA contributes to the role of CD73 in cancer." (PMID 32635260, 2020). "Its co-expression with NT5E on GBM could be related to its role in cancer pathology, emerging from a number of recent studies." (PMID 31547570, 2019). "Publication bias for the prevalence of CD73/NT5E in various cancers." (PMID 29514610, 2018). "An example of proteins enriched in affinity pure EVs of both cancer cell lines was NT5E/CD73, ecto-5′-nucleotidase, which is a plasma membrane protein that catalyses the conversion of extracellular nucleotides to membrane-permeable nucleosides (especially the adenosine release from AMP)." (PMID 25469109, 2014). "Interestingly, many of the DMGs identified had multiple roles and several were potential cancer biomarkers or were previously shown to be implicated in various types of cancers, including ABLIM1, ADAM12, ARHGEF4, FBLN2, ITGA6, LRPAP1, Ly9, NT5E, PITPNC1, PLCG1, OBSCN, RHOH, SPTBN1, SPOCK2 and SPRY1." (PMID 41159936, 2025). "Indeed, NT5E has been reported as a hypoxia-responsive gene, and a previous pan-cancer study revealed that NT5E is overexpressed and correlated with a worse prognosis in several cancer types, including PAAD." (PMID 39911580, 2024).
cancer (continued). "Notably, this included TGF-β (TGFB1, TGFB3), drivers of adenosine-mediated immune suppression (NT5E (CD73), ENTPD1 (CD39)), Wnt pathway ligands (WNT7A, WNT4), IL10 and drivers/markers of cancer-associated fibroblast activation (INHBA, WNT7A, TGFB1, FAP, PDGFRA, PDGFRB)." (PMID 39568014, 2024). "NT5E encodes the protein CD73 (cluster of differentiation 73), a cell surface anchored molecule with ectoenzymatic activity that catalyzes the hydrolysis of AMP into adenosine and phosphate and has been shown to mediate the invasive and metastatic properties of cancers." (PMID 31660858, 2019). "The dysregulation of cell migration, adhesion and invasion regulators, such as MCAM/CD146, ALCAM/CD166, CAR/CXADR, EFNA1, LAMA5, CD73/NT5E and integrins, contributes to cancer progression and metastasis." (PMID 40314078, 2025). "Our analysis indicated a positive correlation between B3GNT5 and immune activation markers, including CD276, PVR, NT5E, STING1, and TNF-SF18, as well as immunosuppressive genes TGF-ΒR1, IL-10PR, KDR, CD274, PDCD1LG2, IL-10, and IDO1 in the pan-cancer cohort." (PMID 39671359, 2024). "CD73 is a cell surface 5’nucleotidase (NT5E) and key node in the catabolic process generating immunosuppressive adenosine in cancer." (PMID 38206570, 2024). "For example, NT5E and TNAP are GPI-anchored proteins that can be released by endogenous phospholipase C cleavage of GPI, via microvesicles or via exosomes from cancer cells." (PMID 35784885, 2022). "Through RNAseq database searches, we investigated the magnitude of expression of the genes involved in adenosinergic pathway, namely, CD39 (ENTPD1 gene), CD73 (NT5E gene), and CD38 (also responsible for eADO generation) among female HER2+ cancers." (PMID 34948316, 2021). "To confirm the role of these two enzymes in controlling cancer cell proliferation, we conducted gene knockout (KO) assays and found that the simultaneous deletion of HPRT1 and NT5E markedly reduced A549 cell proliferation." (PMID 34703880, 2021). "Growing evidence shows that NT5E is a key regulatory molecule in the development of cancer and is highly expressed in a number of cancers, including NSCLC, and silence of NT5E suppresses the cell growth and migration of NSCLC cells." (PMID 34787244, 2021). "Thirdly, we observed an increased expression of several immune checkpoints, including PD-L1 (CD274), PD-L2 (PDCD1LG2), CD73 (NT5E), and galectin-3 (LGALS3) in the nutlin-3 resistant cancer cells." (PMID 35582010, 2021). "We have a particular interest in the 5′-nucleotidases CD73 (NT5E) and cN-II (NT5C2) in cancer cells." (PMID 34831141, 2021). "It is well-recognized that gene expression is regulated epigenetically in cancer, and previous studies showed that methylation in the NT5E CpG island correlates well with downregulated expression of CD73 in several cancers." (PMID 33198064, 2020). "In line with this study, 43 genes (including CLIP4) were downregulated in ovarian cancer tumor samples and reactivated after treatment with 5-Aza-2'-deoxycytidine (5-aza-dC); CLIP4, GULP1, BAMBI, NT5E, and TGFB2 showed a pattern of cancer-specific methylation." (PMID 33575272, 2020). "HIF-1-induced expression of CD73 is triggered by the binding of HIF-1 to the NT5E gene on hypoxic cells, such as cancer cells in solid tumors." (PMID 31396523, 2019). "Evidence from a number of experimental systems suggests that expression of NT5E may be important in increasing the invasive and metastatic properties of some cancer cells and overexpression of NT5E may contribute to progression of cancer via generation of adenosine." (PMID 22454080, 2012).
cancer (continued). "Additionally, MATN3 tends to positively correlate with genes such as CD276, NT5E, and TMEM173 in most cancers." (PMID 41004439, 2025). "Ecto-5-prime-nucleotidase (NT5E; CD73) overexpression has been reported in several human cancers." (PMID 22454080, 2012). "Thus, regulation of Nt5e by Foxp3 appears cell type specific and does not necessarily apply the same way to cancer cells." (PMID 29720980, 2018). "In the TME, a shift towards ATP accumulation might be crucial in mediating an effective antitumour response; thus, depletion of NT5E/CD73 may be clinically relevant as an ICD inducer, supporting the notion that the adenosinergic system is a relevant target in cancer." (PMID 24741617, 2014). "The proof of NT5E/CD73 positive vesicles in body fluids suggests that the EV specific proteins might be suitable as anchors for cancer vesicles, but the source of the vesicles is not restricted to epithelial cells." (PMID 25469109, 2014). "In the EV samples derived from the model cell line HPDE no NT5E/CD73 could be detected, whereas all tested carcinoma cells delivered NT5E/CD73 by vesicle release." (PMID 25469109, 2014). "In concordance with our clinical observation of ENTPD2 overexpression, we further showed that NT5E inhibitor could not prevent the 5′-AMP-induced MDSC maintenance, suggesting that ENTPD2 but not NT5E is critical for MDSC maintenance in the context of cancer." (PMID 28894087, 2017).
infection (60 papers, 2012 to 2026). The state of being infected such as from the introduction of a foreign agent such as serum, vaccine, antigenic substance or organism. "MSP121-specific AMB sorted during chronic P. chabaudi infection, and MSP121-specific Bmem sorted after resolution of the infection shared the expression of a series of mouse memory markers, including Cd80, Fcrl5, Nt5e (CD73), and Cd86." (PMID 30387712, 2018). "Direct evidence for the role of adenosine produced by Nt5e during infection is needed." (PMID 22685551, 2012). "Since Nt5e is widely conserved, the hydrolysis of ATP to immunosuppressive adenosine in vivo may be relevant to the virulence of infection by many species." (PMID 22685551, 2012). "Hence, the consumption of ATP as well as generation of adenosine by S.sanguinis Nt5e could influence the immune response during infection." (PMID 22685551, 2012). "As a surface protein, Nt5e could also be involved in adherence to platelets or platelet vegetations and contribute to nutrient acquisition (i.e., nucleosides) and the persistence of infection." (PMID 22685551, 2012). "Portions of 5’-nucleotidases, such as NudP, AdsA, S5nAi, S5nA, and Nt5e have been shown to convert AMP to Ado and relate to survival in host blood and specific tissues and virulence in animal models of infection." (PMID 39282964, 2024).